FLT3 (fms related receptor tyrosine kinase 3)
Diseases named in the same sentence as FLT3 in open-access papers (continued):
Sharing a sentence is not in itself a finding about the gene and the disease.
acute myeloid leukemia (continued). "Mutations that activate FLT3, including internal tandem duplications (ITDs) and point mutations in the tyrosine kinase domain, are frequently observed in acute myeloid leukemia (AML) cases." (PMID 41471328, 2025). "FMS-like tyrosine kinase 3 (FLT3) is the most frequently mutated gene in acute myeloid leukemia (AML), and is associated with poor prognosis and a high relapse rate." (PMID 40092706, 2025). "FLT3 mutations represent one of the common gene mutations in acute myeloid leukemia (AML), and they can be targeted with an FLT3 inhibitor such as gilteritinib." (PMID 40099175, 2025). "Activating mutations of FMS-like Tyrosine Kinase 3 (FLT3) occur in a subset of patients with acute myeloid leukemia (AML) and confer a poor prognosis." (PMID 40330912, 2025). "The FLT3-ITD mutation plays a significant role in the pathogenesis of acute myeloid leukemia (AML) and represents a potential therapeutic target for the disease." (PMID 39963240, 2025). "Gilteritinib, a pyrazine carboxamide derivative, is an orally available FDA-approved FMS-like tyrosine kinase 3 (FLT3) inhibitor that is used for treating patients with FLT3-mutated acute myeloid leukemia (AML)." (PMID 40157901, 2025). "FLT3mutations represent one of the most frequently observed genetic alterations in adult acute myeloid leukemia (AML), with internal tandem duplication (FLT3-ITD) mutations detected in approximately 30% of cases." (PMID 41150745, 2025). "IMP2 supports glycolytic functions in FLT3-ITD-positive acute myeloid leukemia (AML), a common and aggressive form of AML characterized by an internal tandem duplication mutation in the FLT3 gene." (PMID 40141058, 2025). "Approximately 30% of acute myeloid leukemia (AML) patients harbor FLT3 mutations, which are associated with poor prognosis." (PMID 41231037, 2025). "While FLT3 inhibitors have significantly improved the treatment ofaggressive FLT3-mutated acute myeloid leukemia (AML), the emergence ofresistance remains as a major challenge." (PMID 41270153, 2025). "We describe two FLT3-mutated acute myeloid leukemia (AML) cases with central nervous system (CNS) involvement." (PMID 40083897, 2025). "FLT3 mutations are ubiquitous in acute myeloid leukemia (AML) and are significantly correlated with poor prognostic outcomes." (PMID 39963240, 2025). "Considering the essential role of FLT3-ITD mutations in the development of acute myeloid leukemia (AML), the research and development of FLT3 inhibitors hold significant therapeutic potential." (PMID 39963240, 2025). "Fms-like tyrosine kinase 3 (FLT3) is the most frequently mutated gene in acute myeloid leukemia (AML)." (PMID 38112995, 2024). "FMS-like tyrosine kinase 3 internal tandem duplication (FLT3-ITD) is a common mutation type in acute myeloid leukemia (AML) and is usually associated with poor patient prognosis." (PMID 38978049, 2024). "The patient was diagnosed with acute myeloid leukemia (AML) M5 subtype with FLT3 gene mutation in March 2023." (PMID 39512623, 2024). "Although much progress has been made in improving treatment outcomes for patients with an acute myeloid leukemia (AML) diagnosis, certain subsets of AML, such as those with a FLT3‐ITD mutation, have poor treatment advances and low survival rates." (PMID 38334474, 2024). "We recently demonstrated that a small subset of cells in FLT3-mutated acute myeloid leukemia (AML) cell lines exhibit SORE6 reporter activity and cancer stem-like features including chemoresistance." (PMID 38203816, 2024). "Internal tandem duplication mutations in the fms-like tyrosine kinase 3 (FLT3) gene have been identified in ∼30% of relapsed/refractory acute myeloid leukemia (R/R AML) patients and have been associated with more aggressive disease and worse survival." (PMID 39687070, 2024).
acute myeloid leukemia (continued). "Mutations in the FMS-like tyrosine kinase 3 (FLT3) gene are present in nearly 30% of acute myeloid leukemia (AML) cases." (PMID 39589497, 2024). "Mutations in FLT3 are commonly found inacute myeloid leukemia (AML), a type of cancer that affects the blood and bone marrow." (PMID 39132250, 2024). "FLT3 is frequently mutatedand dysregulated in acute myeloid leukemia (AML), particularly through internal tandem duplication (ITD) mutations." (PMID 39132250, 2024). "FLT3 mutations are found in up to approximately 20–30% of acute myeloid leukemia (AML) patients, are associated with a normal karyotype, and are more frequently found in adults compared to children, with a decreasing incidence above 60 years of age." (PMID 38132393, 2023). "FLT3 mutations are observed in 30% of acute myeloid leukemia (AML) patients, and various FLT3 inhibitors are commonly prescribed for treatment." (PMID 38025707, 2023). "Interestingly, the results of our recent study demonstrated a clear link between increased phosphorylation levels of CDK1 at Tyr15 and the development of resistance to FLT3 inhibitors in acute myeloid leukaemia cells carrying FLT3-ITD mutations, the most common genetic alterations." (PMID 37898722, 2023). "FMS-related tyrosine kinase 3 (FLT3) mutations are detected in approximately 25–30% of acute myeloid leukemia (AML) patients, thus representing one of the most frequent mutations in AML." (PMID 37606693, 2023). "Fms-like tyrosine kinase 3 (FLT3) mutation mechanisms are among the most common genetic abnormalities detected in about 30% of acute myeloid leukemia (AML) patients." (PMID 37438819, 2023). "FMS-like tyrosine kinase 3 (FLT3) mutations are detected in approximately 20–30% of patients with acute myeloid leukemia (AML), with the presence of a FLT3 internal tandem duplication (FLT3-ITD) mutation being associated with an inferior outcome." (PMID 38132393, 2023). "Gilteritinib is the only drug approved as monotherapy for acute myeloid leukemia (AML) patients harboring FMS-like tyrosine kinase 3 internal tandem duplication (FLT3-ITD) mutation throughout the world." (PMID 36691065, 2023). "Activating mutations in FLT3 are seen in ~30% of newly diagnosed acute myeloid leukemia (AML) patients." (PMID 37190240, 2023). "Oncogenic mutations in the type III receptor tyrosine kinase FLT3 are the most commonly identified genetic alterations in acute myeloid leukemia (AML)." (PMID 36835239, 2023). "It is now widely accepted that the class III receptor tyrosine kinase FLT3 mutation status distinguishes a subtype of acute myeloid leukemia (AML) with a poor prognosis." (PMID 37297842, 2023). "Constitutive activation of AKT is identified in up to 70% of acute myeloid leukemia (AML) patients and mediates, at least in part, the leukemogenic effects of activating fms like tyrosine kinase (FLT3) internal tandem duplication (ITD) mutations." (PMID 37877351, 2023). "The FLT3 gene is the most frequently altered gene in acute myeloid leukemia (AML) with mutations occurring in up to 30% of patients, where higher FLT3 expression has been associated with poor overall survival (OS)." (PMID 37174019, 2023). "Acute myeloid leukemia (AML) with FMS-like tyrosine kinase 3 internal tandem duplication (FLT3-ITD) mutation accounts for a large proportion of AML patients and diagnosed with poor prognosis." (PMID 38037057, 2023). "A 69-year-old woman was diagnosed with acute myeloid leukemia (AML) with an FMS-like tyrosine kinase 3-internal tandem duplication (FLT3-ITD) mutation." (PMID 37662831, 2023). "FMS-related tyrosine kinase 3 (FLT3) mutations, present in about 25%-30% of acute myeloid leukemia (AML) patients, constitute one of the most frequently detected mutations in these patients." (PMID 37457126, 2023). "Midostaurin added to intensive chemotherapy is the standard of care for acute myeloid leukemia (AML) with FLT3 mutations (FLT3mut)." (PMID 37147301, 2023).
acute myeloid leukemia (continued). "The type III receptor tyrosine kinase FLT3 is a pivotal kinase for hematopoietic progenitor cell regulation, with significant implications in acute myeloid leukemia (AML) through mutations like internal tandem duplication (ITD)." (PMID 38001685, 2023). "The internal tandem duplication of the juxtamembrane domain of the FMS-like tyrosine kinase 3 (FLT3-ITD) is the most common genetic change in acute myeloid leukemia (AML), and about 30% of all AMLs harbor a FLT3-ITD mutation." (PMID 37391442, 2023). "Mutations of FLT3 (fms-related tyrosine kinase 3) are common gene mutations in acute myeloid leukemia (AML)." (PMID 35922444, 2022). "FMS-like tyrosine kinase 3 (FLT3)-internal tandem duplication (FLT3-ITD) mutations occur in about 25% of all acute myeloid leukemia (AML) patients and confer a poor prognosis." (PMID 36078163, 2022). "Mutations in the gene encoding the FMS-like tyrosine kinase 3 (FLT3) receptor tyrosine kinase occur in approximately 30% of acute myeloid leukemia (AML) cases, with internal tandem duplication (ITD) representing the most common type (25% of AML cases)." (PMID 35741439, 2022). "The in-frame internal tandem duplications (ITDs) of the gene encoding FMS-like tyrosine kinase 3 (FLT3) have been found in approximately 25% of acute myeloid leukemia (AML) cases." (PMID 36551616, 2022). "TKI as post-transplantation maintenance therapy for patients with FLT3-ITD-mutated acute myeloid leukemia (AML) has been investigated in several clinical trials." (PMID 36579521, 2022). "Internal tandem duplications in the FLT3 gene, termed FLT3-ITDs, are useful molecular markers in acute myeloid leukemia (AML) for patient risk stratification and follow-up." (PMID 36307762, 2022). "FLT3 is mutated in approximately 30% of patients with acute myeloid leukemia (AML), and is the most prevalent molecular aberrancy in AML." (PMID 35810308, 2022). "Acute myeloid leukemia (AML) is characterized by distinct genetic abnormalities, such as FLT3-ITD mutation." (PMID 36145344, 2022). "Acute myeloid leukemia (AML), especially the FLT3-ITD mutation subtype, has a poorer prognosis and higher risk of recurrence, which seriously threatens human health." (PMID 36612069, 2022). "Mutations in FLT3, as well known, represent the most common genomic alteration in acute myeloid leukemia (AML), identified in approximately one-third of newly diagnosed adult patients." (PMID 35565314, 2022). "In the present study, we analyzed the expression of 19S proteasome subunits in acute myeloid leukemia (AML) patients with mutations in the FMS-like tyrosine kinase 3 (FLT3) gene and assessed their impact on overall survival (OS)." (PMID 36498916, 2022). "Midostaurin combined with chemotherapy is currently used to treat newly diagnosed acute myeloid leukemia (AML) patients with FMS-like tyrosine kinase 3 (FLT3)-mutations." (PMID 35810308, 2022). "Activating FLT3 mutations are the most common mutations in acute myeloid leukemia (AML), but the optimal threshold of FLT3/ITD allelic ratio (AR) among pediatric AML patients remains controversial." (PMID 35760968, 2022). "Internal tandem duplication (ITD) and tyrosine kinase domain (TKD) mutations in the FLT3 gene are some of the most common mutations in patients with newly diagnosed acute myeloid leukemia (AML)." (PMID 35501304, 2022). "The FLT3-ITD mutation occurs in about 30% of acute myeloid leukemia (AML) and is associated with poor prognosis." (PMID 35656547, 2022). "FMS-like tyrosine kinase 3 (FLT3) is among the most common driver genes recurrently mutated in acute myeloid leukemia (AML), accounting for approximately 30% of cases." (PMID 34660293, 2021). "FMS-like tyrosine kinase 3 (FLT3) internal tandem duplication (ITD) mutations in patients with acute myeloid leukemia (AML) are associated with early relapse and poor prognosis." (PMID 33577442, 2021).
acute myeloid leukemia (continued). "FLT3-internal tandem duplications, for example, are driving acute myeloid leukemia (AML) and their occurrence is linked to a poor prognosis." (PMID 34376693, 2021). "FLT3 mutations are the most frequently identified genetic alterations in acute myeloid leukemia (AML) and are associated with poor clinical outcome, relapse and chemotherapeutic resistance." (PMID 33925552, 2021). "The FMS-like tyrosine kinase 3 (FLT3) gene is mutated in one-third of patients with de novo acute myeloid leukemia (AML)." (PMID 34360855, 2021). "Mutations of the FLT3 gene are detected in around a third of patients with de novo acute myeloid leukemia (AML)." (PMID 34360855, 2021). "In treating acute myeloid leukemia (AML), FLT3 gene F691L mutation shows universal resistance to all currently available FLT3 inhibitors." (PMID 34760927, 2021). "Overexpression and frequent mutations in FMS-like tyrosine kinase-3 (FLT3) are considered risk factors for severe acute myeloid leukemia (AML)." (PMID 34830393, 2021). "FMS-like tyrosine kinase-3 (FLT3) is one of the most frequently mutated genes in acute myeloid leukemia (AML), accounting for 30% of adult AML cases, with internal tandem duplication (ITD) mutations appearing in 24% of adult AML patients." (PMID 35011583, 2021). "The FLT3 inhibitor gilteritinib has clinical activity in patients with FLT3‐mutated (FLT3mut+) relapsed/refractory (R/R) acute myeloid leukemia (AML)." (PMID 33340276, 2021). "Oximes can also inhibit FMS-like tyrosine kinase-3 (FLT3), which is recognized as a drug target for the treatment of acute myeloid leukemia (AML), as activating mutations of FLT3 have been found in ~30% of AML patients." (PMID 34067242, 2021). "OBJECTIVES: Internal tandem duplications (ITDs) of the Fms-like tyrosine kinase 3 (FLT3) represent the most frequent molecular aberrations in acute myeloid leukemia (AML) and are associated with an inferior prognosis." (PMID 34831215, 2021). "Compared with patients with acute myeloid leukemia (AML) without FLT3-ITD mutations, circMYBL2 is expressed higher in AML patients with FLT3-ITD mutations, and its mechanism is mainly increased." (PMID 33880120, 2021). "Internal tandem duplication (-ITD) mutations of Fms-like tyrosine kinase 3 (FLT3) provide growth and pro-survival signals in the context of established driver mutations in FLT3 mutant acute myeloid leukemia (AML)." (PMID 33658483, 2021). "The presence of FMS-like tyrosine kinase 3-internal tandem duplication (FLT3-ITD) is one of the most frequent mutations in acute myeloid leukemia (AML) and is associated with an unfavorable prognosis." (PMID 34172833, 2021). "About 25% of patients with acute myeloid leukemia (AML) harbor FMS-like tyrosine kinase 3 (FLT3) internal tandem duplication (ITD) mutations and their prognosis remains poor." (PMID 34099621, 2021). "The FMS-like tyrosine kinase 3 (FLT3)- internal tandem duplication (ITD) mutation can be found in approximately 25% of all acute myeloid leukemia (AML) cases and is associated with a poor prognosis." (PMID 33796529, 2021). "Constitutive activation of FMS-like tyrosine kinase 3 (FLT3) occurs in approximately 30% of acute myeloid leukemias (AML) and is clinically associated with an aggressive disease course and higher rates of relapse." (PMID 34686212, 2021). "Activating mutations of FLT3 associated with a poor prognosis in acute myeloid leukemia (AML) and FLT3 inhibitors have an important role in high-risk patients." (PMID 34178637, 2021). "PRMT5 activity possesses myeloproliferative effects that stem from its interaction with receptor tyrosine kinase FLT3, a protein often mutated in acute myeloid leukemia (AML)." (PMID 33440687, 2021). "FLT3-ITD mutations are detected in approximately 25% of newly diagnosed adult acute myeloid leukemia (AML) patients and confer an adverse prognosis." (PMID 34671057, 2021).
acute myeloid leukemia (continued). "FMS-like tyrosine kinase 3 (FLT3) gene mutations have been found in more than one-third of Acute Myeloid Leukemia (AML) cases." (PMID 34299222, 2021). "MOLM-13 cells harbor the internal tandem duplication (ITD) in-frame insertion in FLT3, a gene mutated in ~30% of acute myeloid leukemia (AML) patients and associated with poor prognosis." (PMID 34533995, 2021). "Examples include Philadelphia Chromosome-positive B-cell acute lymphoblastic leukemia (Ph+ B-ALL), Ph-like B-ALL, and acute myeloid leukemia (AML) with Flt3 mutations." (PMID 34737376, 2021). "FLT3-ITD has been recently used as a molecular prognostic marker for risk classification in acute myeloid leukemia (AML) therapy." (PMID 32944043, 2020). "Internal tandem duplication (ITD) mutations of FMS-like tyrosine kinase-3 (FLT3) are the most frequent genetic alterations in acute myeloid leukemia (AML) and predict a poor prognosis." (PMID 32296014, 2020). "In acute myeloid leukemia (AML), internal tandem duplication mutations in the FLT3 tyrosine kinase receptor (FLT3-ITD) are associated with a dismal outcome." (PMID 32393312, 2020). "Acute myeloid leukemia (AML) with FLT3-ITD mutations (FLT3-ITDmut) remains a therapeutic challenge, with a still high relapse rate, despite targeted treatment with tyrosine kinase inhibitors." (PMID 32843624, 2020). "Internal tandem duplication (ITD) in the FLT3 gene is one of the most frequent mutations found in acute myeloid leukemia (AML)." (PMID 32722211, 2020). "For example, ITDs in FLT3 are discovered in ∼20%–30% of patients with acute myeloid leukemia (AML) and have been associated with increased relapse risk and decreased overall survival." (PMID 32852038, 2020). "In 1996, an internal tandem duplication in the JM domain-encoding region of FLT3 (FLT3-ITD) was identified in acute myeloid leukemia (AML) cells." (PMID 32722298, 2020). "FLT3 internal tandem duplication (ITD) mutations are associated with poor prognosis in patients with acute myeloid leukemia (AML)." (PMID 32215183, 2020). "FLT3 tyrosine kinase receptor protein (CD135) was analyzed in an acute myeloid leukemia (AML) patient with FLT3 ITD mutation displaying clusters of positive AML cells within adipocytes and stromal tissue." (PMID 32825035, 2020). "Berenstein studies show that FLT3 gene mutation is one of the most frequent gene mutations in patients with Acute myeloid leukemia (AML), which can be seen in various subtypes of AMI." (PMID 32316985, 2020). "Fms-like tyrosine kinase 3 (FLT3) mutation is one of the most common mutations in acute myeloid leukemia (AML)." (PMID 32637351, 2020). "Internal tandem duplication (ITD) mutation in Fms-like tyrosine kinase 3 gene (FLT3/ITD) accounts for approximately 30% of acute myeloid leukemia (AML) cases." (PMID 32641978, 2020). "Acute myeloid leukemia (AML) is a haematologic disease in which oncogenic mutations in the receptor tyrosine kinase FLT3 frequently lead to leukaemic development." (PMID 33003568, 2020). "Internal tandem duplication (ITD) of FMS-like tyrosine kinase 3 (FLT3) is the most common mutation in patients with acute myeloid leukemia (AML)." (PMID 33167505, 2020). "Therapeutic effects of FLT3 inhibitors have been reported in acute myeloid leukemia (AML) with constitutively activating FLT3 mutations, including internal tandem duplication (ITD) and point mutation, which are found in approximately one-third of AML patients." (PMID 31692922, 2019). "Relapse of FLT3‐mutated acute myeloid leukemia (AML) following allogeneic stem cell transplantation is associated with poor survival." (PMID 31893105, 2019). "In addition, natural product derivative Midostaurin has been approved by the US FDA for the treatment of FLT3-mutated acute myelogenous leukemia (AML), and synthetic indolocarbazole derivative D shows excellent antibacterial activity and good antifungal activity." (PMID 30857232, 2019).